ENSG00000289027 (novel protein)
Gene: Protein-coding gene on chromosome 7 (92,112,176 to 92,245,924, reverse strand). Ensembl gene ENSG00000289027.
Genetic constraint (gnomAD): Loss-of-function variants: 46 observed, 66.44 expected, observed/expected ratio (o/e) 0.69, 90% interval 0.55 to 0.88. Missense variants: 576 observed, 741.81 expected, observed/expected ratio (o/e) 0.78, 90% interval 0.72 to 0.83. Synonymous variants: 206 observed, 245.31 expected, observed/expected ratio (o/e) 0.84, 90% interval 0.75 to 0.94.